RN7SL444P (RNA, 7SL, cytoplasmic 444, pseudogene)
Gene: Miscellaneous RNA gene on chromosome 1 (151,300,665 to 151,300,964, reverse strand). Ensembl gene ENSG00000265753.
Homologues: Orthologues: chimpanzee Metazoa_SRP (99% identical), macaque Metazoa_SRP (92% identical). Paralogues in human: RN7SL2 (88% identical), RN7SL1 (86% identical), RN7SL3 (85% identical), RN7SL769P (84% identical), RN7SL493P (84% identical), RN7SL44P (83% identical), RN7SL45P (83% identical), RN7SL326P (82% identical), RN7SL300P (82% identical), RN7SL480P (82% identical), RN7SL543P (82% identical), RN7SL147P (81% identical), and 705 more.